CCL22 (C-C motif chemokine ligand 22)
Diseases named in the same sentence as CCL22 in open-access papers (continued):
Sharing a sentence is not in itself a finding about the gene and the disease.
atopic dermatitis (continued). "In addition, the expression of IL-4, IL-13, CXCL10, CCL5, CCL17, and CCL22, which are atopic dermatitis mediators, increased 2- or 3-fold in HaCaT cells treated with DPM compared with that in the control group." (PMID 39599592, 2024). "In addition, the gene expression levels of IL-4, IL-13, CXCL10, CCL5, CCL17, and CCL22, which are related to atopic dermatitis, were significantly decreased by HCFE in DPM-stimulated HaCaT cells." (PMID 39599592, 2024). "Plasma concentrations of CCL27 and CCL22 were found to correlate positively with SCORing atopic dermatitis (SCORAD), objective SCORAD, % area affected, lichenification and disease intensity, and CCL27 also correlated positively with pruritus in AD patients (all p < 0.05)." (PMID 27077833, 2016). "The macrophage-derived chemokine CCL22 has been recognized as a type 2 T helper cell (Th2) chemokine, and its involvement in allergic diseases, such as atopic dermatitis, bronchial asthma, and eosinophilic pneumonia, has been revealed." (PMID 39808500, 2025). "Atopic dermatitis is caused by chronic inflammation of the skin tissue, and the onset of atopic dermatitis is closely related to various inflammatory mediators such as IL-4, IL-13, CCL5, CCL17, and CCL22." (PMID 39599592, 2024). "MDC/CCL22 acts as a Th2 skewed chemoattractant, upregulates TARC/CCL17 production, and has been found to correlate with atopic dermatitis disease activity." (PMID 38582943, 2024). "TNF-α/IFN-γ, which is extensively employed in atopic dermatitis simulations, acts on HaCaT cells and induces them to release chemokines and cytokines, such as IL-6, IL-8, CCL17, and CCL22." (PMID 37110740, 2023). "According to previous studies, epithelial cells and keratinocytes damaged by atopic dermatitis produce proinflammatory cytokines (such as TNF-α, IL-1β, IL-6, and IL-8) and chemokines (such as CCL17/TARC, CCL22/MDC)." (PMID 36793948, 2023). "After 2,4-dinitrochlorobenzene (DNCB) induction in mice with atopic dermatitis, FA effectively reduced the symptoms and serum levels of CCL17 and CCL22." (PMID 37110740, 2023). "Our date showed that VAE inhibited CCL17 and CCL22 levels in TNF-α/IFN-γ-stimulated HaCaT keratinocytes and DNCB-induced atopic dermatitis animal models." (PMID 36793948, 2023). "In atopic dermatitis, damaged epithelial cells and keratinocytes produce proinflammatory cytokines and chemokines such as TNF-α, IL-1β, IL-6, IL-8, CCL17, and CCL22." (PMID 36158872, 2022). "Together with CCL22, which showed a 24-fold overexpression in CD11b+CD11c+ MDSCs, both chemokines are known to attract CCR4-bearing Th2 cells and serve as markers for the severity of Th2-mediated atopic dermatitis." (PMID 34721430, 2021). "A recent study has shown by immunohistochemistry that CCL22 is not expressed in normal skin and is markedly expressed in the lesions of atopic dermatitis, allergic contact dermatitis, and psoriasis vulgaris." (PMID 22125604, 2011). "Similarly, CCR4-involving cell-cell communication, with the ligands CCL5, CCL17, CCL22, also showed diseased organ specificity, but in nonlesional atopic dermatitis and psoriatic skin." (PMID 40809141, 2024). "Although the exact mechanism and treatment for atopic dermatitis have not been found, controlling the excessive production of TARC/CCL17 and MDC/CCL22 may be the key to treatment." (PMID 35335198, 2022).
melanoma (30 papers, 2016 to 2024). A malignant, usually aggressive tumor composed of atypical, neoplastic melanocytes. "POSTN causes the stimulation of CD163 + macrophages to produce several cytokines including Treg-associated chemokines [chemokine ligand 17 (CCL17), CCL22] which in turn induce the recruitment of Tregs to the tumor site in melanoma." (PMID 39003350, 2024). "Cutaneous and brain-metastasizing melanoma variants stimulated with the CCR4 ligand CCL22, showed a differential AKT phosphorylation pattern." (PMID 28415693, 2017). "The use of certain chemotherapy agents, such as nimustine hydrochloride, dacarbazine, and vincristine, has been shown to decrease CCL22 production in B16F10 melanoma mice." (PMID 37525217, 2023). "So, it was concluded that tumor-infiltrating CD11c+ dendritic cells are the predominant source of CCL22 in the TME of B16F10 melanoma." (PMID 37122749, 2023). "Higher expression of chemokines (e.g., CCL17 and CCL22) that attract anti-tumor immune cells was found in FGFR mutant melanoma." (PMID 36426352, 2022). "Another study using human melanoma brain metastasis xenografts showed that metastatic melanoma cells stimulated with CCL22 showed a differential AKT phosphorylation pattern, which is associated with tumor cell survival and proliferation." (PMID 33466236, 2021). "In another report, IFN-β decreases the production of CCL22 from TAMs in B16F10 melanoma, leading to suppression of tumor growth by the modulation of TIL profiles in vivo." (PMID 32707850, 2020). "Also, in B16F10 melanoma mice that were treated with cytotoxic antimelanoma drugs such as dacarbazine, nimustine hydrochloride, and vincristine, the production of CCL22 was reduced." (PMID 39003350, 2024). "In vitro studies showed that CCL-22 gene expression was downregulated by about 60% in B16-F10 melanoma cells, and CCL-22, IL-10, and TGF-β gene expression was downregulated by about 64%, 50%, and 50% in RAW264.7 macrophages, respectively, after 10 μM CUR@PPC treatment." (PMID 37403095, 2023). "Repolarizing TAMs by immunomodulators such as imiquimod and IFNs may inhibit melanoma tumor growth as TAMs generated by CCL17 and CCL22 attract Tregs to melanoma tumor locations." (PMID 37525217, 2023). "A study of individual CSF samples from 22 patients with melanoma brain metastases and 5 disease-free controls found that Chemokine CCL22 and cytokines IL-1α, IL-4, and IL-5 were reduced in most samples, whereas a subset of molecules including CXCL10, CCL4, CCL17, and IL8 increased expression." (PMID 36527157, 2022). "A small molecule antagonist of the CCR4‐CCL17/CCL22 axis reduced the malignancy of melanoma cells." (PMID 32761606, 2021). "CM derived from bcl-2 overexpressing melanoma cells treated with IL-1β blocking antibody caused a strong inhibition of M2 macrophage polarization, resulting in significant reduction of M2 (CD206, CCL1, CCL22) and induction of M1 (COX-2 and IL-12) markers." (PMID 32269145, 2020). "Baseline serum CXCL5, but not CXCL10 and CCL22, is associated with the efficacy of nivolumab in advanced melanoma." (PMID 32707850, 2020). "Both RNAseq and NanoString analyses showed that melanoma tumors grown in Siah2−/− mice exhibit reduced expression of Ccl17 and Ccl22, chemokines expressed by tolerogenic DCs49,50, along with increased expression of Cxcl9, a chemokine functioning in T cell recruitment to tumor sites." (PMID 31911617, 2020). "Notably, cBioPortal analysis of TCGA data relevant to CCL22 expression in melanoma patients revealed a strong positive correlation between CCL22 and FOXP3 mRNA expression (Pearson = 0.66, Spearman = 0.77, P = 0.02)." (PMID 31911617, 2020). "Furthermore, levels of CCL17 mRNA correlated positively with levels of CCL22 mRNA expression (Pearson = 0.62, P = 0.06), findings that link our observations in Siah2−/− mice to clinical outcomes seen in melanoma patients." (PMID 31911617, 2020).
melanoma (continued). "In addition the reduction of CCL22 by TAMs decreases Tregs in the tumor site, which enhances the therapeutic effects of immune therapy in the mouse melanoma model." (PMID 31080803, 2019). "The downregulation of CCL22 production was also observed in B16F10 melanoma mouse treated with classical cytotoxic anti-melanoma drugs such as dacarbazine, nimustine hydrochloride, and vincristine, all of which have been used in the adjuvant setting for advanced melanoma for the last 30 years." (PMID 29410946, 2018). "Chemokines CCL17 (Thymus and activation regulated chemokine (TARC)) and CCL22 (C-C motif chemokine 22) produced by tumour infiltrating macrophages may help to recruit Tregs to tumour and maintain an immunosuppressive tumour microenvironment in melanoma." (PMID 29236046, 2017). "Notably, the expression of the CCR4 ligands, Ccl22 and Ccl17 is upregulated at the earliest stages of brain metastasis, and precedes the infiltration of melanoma cells to the brain." (PMID 28415693, 2017). "Further, analysis of clusters identified within the melanoma patient set comparing patient outcome suggests that suppression of IL-1α, IL-4, IL-5, and CCL22, with concomitant elevation of CXCL10, CCL4, and CCL17, may correlate with more aggressive development of brain metastasis." (PMID 36527157, 2022). "CCL22 could recruit T regulatory cells and controlled the growth of tumor cells in melanoma." (PMID 35664768, 2022). "Indeed, intratumoral administration of anti-CCL22 antibody inhibited B16F10 melanoma growth by decreasing Treg recruitment at the tumor site, suggesting that a reduction in tumor-derived CCL22 could suppress melanoma growth." (PMID 31616630, 2019). "Regarding chemokines, CCL1, CCL17, CCL22 and CCL23, were significantly increased in FGFR Mut melanoma (all P < 0.05)." (PMID 36426352, 2022). "In melanoma, CCL22 boosts Treg recruitment into the TME while inhibiting anticancer immunity and in colorectal adenocarcinomas, CCL22 mRNA expression is considerably higher in tumor tissue than in corresponding normal tissue." (PMID 35935989, 2022). "A study from our laboratory established that the chemokine receptor CCR4 is a member of the molecular signature of melanoma brain metastasis and that its chemokine ligands CCL17 and CCL22 are expressed in microenvironmental brain cells." (PMID 32761606, 2021). "Cross talk between melanoma cells and microglia, astrocytes and brain endothelial cells (EC) upregulated CCR4 expression on melanoma cells and CCL17/CCL22 expression by and secretion from the brain cells." (PMID 32761606, 2021). "CCL1 and CCL22, the main ligands for CCR8 and CCR4, respectively, have been shown to be upregulated both at the gene and protein levels in the TME of melanoma, suggesting that melanoma cells are able to actively recruit T-regs." (PMID 34830780, 2021). "Further analyses show that SK1 knockdown in melanoma tumors potently reduced the production of various immunosuppressive cytokines such as TGFβ, IL10, CCL17, and CCL22, which is in line with the strong decrease of Treg tumor infiltration." (PMID 31974367, 2020). "In contrast, an increased expression of CCL22 in the tumor improves prognosis in lung cancer patients and elevated CCL17 blood levels improve prognosis in melanoma patients." (PMID 33182504, 2020). "In a B16F10 melanoma model, imiquimod (IQM) has been shown to reduce T-regs at the tumor site by the downregulation of CCL22 production." (PMID 31842422, 2019). "Immunomodulatory reagents such as IFNs and imiquimod reduce CCL22 from TAMs, leading to the therapeutic effects of them in mouse B16F10 melanoma models." (PMID 29410946, 2018). "In another study, we showed that brain microenvironmental cells including astrocytes expressed and released CCL17 and CCL22 two chemokine ligands of the chemokine receptor CCR4, which is expressed by a subpopulation of melanoma cells with brain‐metastasizing capacity." (PMID 32761606, 2021).
melanoma (continued). "PAI-1 decreased the production of CXCL10 and CCL22, suggesting that PAI-1 might decrease the TILs in melanoma." (PMID 34912726, 2021). "Because CCL17 and CCL22 from TAMs attracts Tregs to the tumor site in melanoma, repolarization of TAMs by immunomodulatory reagents such as IFN-β and imiquimod are useful for suppressing tumor growth in melanoma." (PMID 29410946, 2018). "We next asked whether astrocyte-induced melanoma cell migration could be mediated by the CCR4 ligands CCL17 and/or CCL22." (PMID 28415693, 2017). "In line with our hypothesis, microglial cells co-cultured with melanoma cells secreted higher levels of both CCL17 and CCL22 than microglial cells grown alone." (PMID 28415693, 2017). "Using a human chemokine array, we measured the secretion level of CCL17 and CCL22 from 3D cultures of microglial cells cultured with or without melanoma cells." (PMID 28415693, 2017). "Their results demonstrated that CCL17 (but not CCL22) was sufficient to enhance melanoma cell invasiveness in the brain, and blocking CCR4 in vivo using a CCR4-antagonist small molecule reduced the tumorigenicity and micrometastasis formation of melanoma cells." (PMID 33466236, 2021). "In addition, TAMs are prominent in the tumor stroma in melanoma, and POSTN stimulates CD163+ macrophages to produce several specific cytokines including Treg-related chemokines [chemokine ligand 17 (CCL17), CCL22]." (PMID 29410946, 2018). "CCL22 is apparently not involved in the migratory function of melanoma cells." (PMID 28415693, 2017). "Notably, TAM-related chemokines, such as CXCL5, CXCL10, and CCL22, as well as a TAM-activation marker, soluble (s)CD163, could be predictive markers for efficacy and immune-related adverse events (irAEs) in anti-PD1 Abs-treated advanced melanoma patients." (PMID 34912726, 2021). "Transwell migration assays using recombinant CCL17 or CCL22 revealed that CCL17, but not CCL22 (data not shown), significantly facilitated migration of the CCR4hi cells compared to control cells (CON), indicating that expression of CCR4 facilitates melanoma cell migration." (PMID 28415693, 2017).
gastric cancer (19 papers, 2012 to 2024). A primary or metastatic malignant neoplasm involving the stomach. "CCL22 has been shown to regulate chemotaxis and to be involved in the recruitment of T cells and other immune cells in breast, ovarian, and gastric cancers and leukemia." (PMID 39408697, 2024). "Macrophages in milky spots produce MDC/CCL22 and its receptor CCR4, which are highly expressed in the omentum and the diaphragm underlining, contributing to gastric cancer cell survival and growth." (PMID 36614904, 2022). "Studies have found that CCL22 is dysregulated in various cancers such as gliomas, breast, gastric cancers and plays an important role in tumor metastasis and immune system function." (PMID 35396377, 2022). "For this reason, chemokines such as CCL1/I-309 (in breast cancer), CCL17/TARC, CCL22/MDC (in gastric cancer and hepatocellular carcinoma), and CCL28/MEC (in hepatocellular carcinoma) cause Treg recruitment into the tumor niche." (PMID 33114763, 2020). "It has been found that the accumulation of CCL22 in the immune microenvironment of gastric cancer is related to the infiltration of regulatory T cells in gastric cancer." (PMID 33426088, 2020). "CCL5, CCL22, CCL21, CCL2, and CCL15 were correlated with effector memory CD4 T cell in T1/T2 stage gastric cancer, and the number of cells was associated with the expression of IL3, IL17F, IL18, IL22, and IL31." (PMID 33426088, 2020). "RT-qPCR results also showed higher levels of CD163, CD204, CD206, IL-10, and CCL-22 mRNA in peripheral blood-derived macrophages selected from gastric cancer patients than from healthy controls." (PMID 31801938, 2019). "CCL22 significantly increased the proliferation ability of gastric cancer cells, and concentrations of CCL22 between 10–100 ng/ml significantly increased migration of MFCs." (PMID 25245466, 2014). "Macrophages in omental milky spots not only have cytotoxic properties against tumour cells, but they also produce CCL22, which helps gastric cancer cells survive and grow into solid metastases." (PMID 25245466, 2014). "In a study on gastric cancer, CCL22 and CCL17 appeared to be both important in recruiting TReg cells to such tumors as demonstrated by in vitro migration assays." (PMID 23533029, 2013). "CCL22 significantly increased the migration of gastric cancer cells." (PMID 39513112, 2024). "Furthermore, the significant correlation between CCL17 or CCL22 chemokines and the number of tumor-infiltrating TReg cells was found in patients with neoplastic meningitis and gastric cancer." (PMID 22481922, 2012). "Besides, CCL22 predicts postoperative prognosis in patients with stage II/III gastric cancer." (PMID 31842422, 2019).
allergic disease (18 papers, 2012 to 2025). An immune response that occurs following re-exposure to an innocuous antigen, and that requires the presence of existing antibodies against that antigen. "CCL22 has also been implicated in various diseases, including allergic disease, and lymphoma." (PMID 30467506, 2018). "The predominant expression of CCR4 in Th2 cells, as well as the upregulation of CCL17 and CCL22 in allergic diseases, have captured attention for their potential therapeutic targeting of CCR4 in the treatment of allergies." (PMID 33669094, 2021). "CCL22 is thought to be involved in several conditions, including allergy, autoimmunity, and tumor growth, and increased CCL22 expression has been reported in autoinflammatory skin diseases." (PMID 34575163, 2021). "It is well known that the CCR4 and its ligands CCL17 and CCL22 played an important role in allergic diseases." (PMID 29118379, 2017). "CCL24, CCL17 and CCL22 were increased in OVA immunized mice in comparison to the adjuvant immunized mice as expected in the current model for allergy." (PMID 27580126, 2016). "Considering that Th2-related genes such as Tnsf4 and Ccl22 are also transactivated by PU.1 in DCs, Spi1 knockdown may be a favorable strategy for allergic diseases." (PMID 30718772, 2019). "Moreover, high cord blood levels of CCL17 and CCL22 were shown to precede allergy development during the first 6 years of life." (PMID 29966024, 2018). "Increased CCL22 expression has been observed in allergy and inflammatory skin responses." (PMID 29099057, 2017). "Notably, the decoy GPN279 and GPN136 molecules validate CCL17 and CCL22 as therapeutic targets in allergy and create a path for its potential to be realized." (PMID 26442456, 2015). "This indicates that dietary GOS facilitates budesonide treatment in its capacity to further decrease allergy driving mediators IL-33, CCL17 and CCL22, derived from both airway epithelial cells and DC." (PMID 30405619, 2018). "Th9 cells were initially studied in allergic diseases and autoimmune diseases, and they promote the development of allergic diseases by promoting the expression of the Th2 cell-related chemokines CCL17 and CCL22." (PMID 32228589, 2020). "Despite its critical involvement in several allergic diseases, the expression mechanism of the Ccl22 gene is not fully understood." (PMID 30718772, 2019). "According to these studies, targeting the interactions between CCL17/CCL22 and CCR4 may be a useful approach for controlling allergic diseases." (PMID 30718772, 2019). "This indicates that there is a potential for molecules that could effectively and specifically neutralize CCL17 or CCL22 i) to help understand the role of CCL17 and/or CCL22, and ii) to develop new therapeutic strategies for allergic diseases." (PMID 26442456, 2015).